OMP (olfactory marker protein)
Description:
May act as a modulator of the olfactory signal-transduction cascade.
Tractability: PROTAC: ubiquitination databases record sites on it.
Gene: Protein-coding gene on chromosome 11 (77,102,840 to 77,103,331, forward strand). Ensembl gene ENSG00000254550.
Subcellular location: Cytoplasm
Gene Ontology:
Biological process: chemical synaptic transmission; sensory perception of smell; signal transduction
Cellular component: axon; cytosol; neuronal cell body; nucleus; cytoplasm; synapse
Genetic constraint (gnomAD): Loss-of-function variants: 6 observed, 12.49 expected, observed/expected ratio (o/e) 0.48, 90% interval 0.26 to 0.95. The upper end of that interval is the gene's LOEUF score, 0.95, which puts it in group 4 of 6, group 1 being the genes least tolerant of losing a copy. Missense variants: 237 observed, 233.65 expected, observed/expected ratio (o/e) 1.01, 90% interval 0.91 to 1.13. Synonymous variants: 81 observed, 104.11 expected, observed/expected ratio (o/e) 0.78, 90% interval 0.65 to 0.94.
Homologues: Orthologues: macaque OMP (94% identical), mouse Omp (90% identical), zebrafish ompb (50% identical), zebrafish ompa (50% identical).
Diseases named in the same sentence as OMP in open-access papers:
OMP is named in the same sentence as 37 diseases in open-access papers, as found by Europe PMC text mining. Sharing a sentence is not in itself a finding about the gene and the disease. The quoted sentences say what the papers report.
Anosmia (2 papers, 2018 to 2024). An inability to perceive odors. "Recent studies have also confirmed that in persistent anosmia after +COVID-19 infection, the relative reduction in mature OMP neurons can explain the hyposmia." (PMID 38685946, 2024). "The similarity in the insufficiency of recovery of OMP+ ORN numbers and olfaction following cessation of CSS administration suggested that damage to the OMP+ ORNs may underlie CSS-induced hyposmia and anosmia." (PMID 29950987, 2018).
diphtheria (2 papers, 2024). A Gram-positive bacterial infection caused by Corynebacterium diphtheriae. "Haemophilus influenzae type b (Hib)Monovalent vaccines:PedvaxHIB: Neisseria meningitidis outer membrane protein complex (Hib-OMP).ActHIB: tetanus toxoid (Hib-TT).HibTITER: the nontoxic mutant of Corynebacterium diphtheriae toxin (Hib-CRM197).proHIBiT: diphtheria toxoid (Hib-DT)." (PMID 39044946, 2024).
pertussis (2 papers, 2010 to 2024). A contagious bacterial respiratory infection caused by Bordetella pertussis. "Seven are known pertussis antigens includingPertactin, Serum resistance protein, chaperonin GroEL and two OMP porins.Sixteen have been documented to be immunogenic in other pathogens but not inB.p, and the immunogenicity of the last seven proteinswas found for the first time." (PMID 21170113, 2010).
viral infection (2 papers, 2023 to 2024). "It should also be noted that Bex1 and 2 were found to be colocalized with the olfactory marker protein in mature olfactory receptor neurons, suggesting a mechanism for loss of smell in the host after viral infection." (PMID 38107402, 2023). "Costaining of NP with neuronal markers TUBB3 (immature) and OMP (mature) revealed viral infection in a subset of cells from the neuronal lineage in the basal half of epithelium." (PMID 38483537, 2024).
adenoma (1 paper, 2018). A neoplasm arising from the epithelium. "An immunohistochemical analysis revealed that OMP was expressed in PRL-secreting cells of normal human pituitary tissue, but was almost undetectable in adenoma tissue." (PMID 29622766, 2018). "To confirm the regulation of PRL by OMP in the human pituitary, we analyzed OMP expression in normal pituitary and PRL-secreting adenoma (prolactinoma) tissue samples by western blotting." (PMID 29622766, 2018).
allergic rhinitis (1 paper, 2025). Inflammation of the nasal mucous membranes caused by an IgE-mediated response to external allergens. "Moreover, in two mouse models of allergic rhinitis, OMP expression in the olfactory epithelium is reduced and accompanied by an increased time period to find hidden pellets in the buried food test, compared to control mice." (PMID 41206615, 2025).
atherosclerosis (1 paper, 2016). A disease characterized by the build-up of fatty material and calcium deposition in the arterial wall resulting in partial or complete occlusion of the arterial lumen. "Nasal immunization with the OMP of Porphyromonas gingivalis was previously shown to be protective against accelerated atherosclerosis induced by intraperitoneal inoculation of bacteria in ApoE−/− mice." (PMID 27383250, 2016).
autoimmune liver disease (1 paper, 2010). "The rates of ASCA and anti-OMP PlusTM positivity were not overall different overall in patients with autoimmune liver disease without cirrhosis as compared to the controls." (PMID 20886039, 2010).
breast carcinoma (1 paper, 2023). "OR51E1 and OMP were strongly expressed in the SI-NET cell line GOT1 and in the SI-NEC (neuroendocrine carcinoma) cell line P-STS and weakly expressed in the breast cancer cell line MCF10A." (PMID 36959559, 2023).
Cirrhosis (1 paper, 2010). A chronic disorder of the liver in which liver tissue becomes scarred and is partially replaced by regenerative nodules and fibrotic tissue resulting in loss of liver function. "ASCA and anti-OMP PlusTM antibodies were present in 38.5% and 62.6% of patients with cirrhosis and in 16% and 20% of controls, respectively (p<0.001)." (PMID 20886039, 2010). "The aim of our study was to investigate the prevalence of ASCA and anti-OMP PlusTM antibodies in a large Hungarian cohort of patients with chronic liver disease of different etiologies with or without cirrhosis." (PMID 20886039, 2010).
conductive disorders (1 paper, 2016). "Because the number of cells expressing OMP, a marker of mature OSNs, on the occluded side did not change compared with that on the open side (4 mice, Mann-Whitney U-test, p = 0.34), and this decrease in the OSN axon activity is consistent with conductive disorders." (PMID 27734933, 2016).
diabetes (1 paper, 2022). "This study may provide a rationale for novel treatment regimens for diabetes by targeting OMP or OR signaling to modulate glucagon secretion." (PMID 36104518, 2022). "In the current study, the number of OMP-positive cells was found to be higher in the pancreatic tissues of the patients with diabetes than in those of the nondiabetic individuals." (PMID 36104518, 2022). "First, we compared the expression patterns of OMP in human pancreatic islets of nondiabetic individuals and patients with diabetes." (PMID 36104518, 2022).
fibrosis (1 paper, 2020). the formation of excess fibrous connective tissue in an organ or tissue in a reparative or reactive process. "After having established a functional role for RSPO3 in liver fibrosis, we next sought to examine if OMP-131R10 could be a therapeutic agent to treat fibrosis and whether OMP-131R10 possesses broad anti-fibrotic activity." (PMID 32160239, 2020).
haemorrhagic septicaemia (1 paper, 2014). "Comparative analysis of the outer membrane protein profiles of haemorrhagic septicaemia associated P. multocida by immunoblotting studies indicated that the major OMP of P. multocida (B: 2) is highly antigenic and 37 kDa OMP has potential for protective and immunodiagnostic studies." (PMID 25028620, 2014).
Hyperglycemia (1 paper, 2022). An increased concentration of glucose in the blood. "We hypothesized that the significant resistance against STZ-induced hyperglycemia in the OMPlox/lox;GCGcre/w mice was caused by altered glucagon secretion from OMP-deleted α-cells." (PMID 36104518, 2022). "Our findings provide evidence that OMP expression in α-cells has a physiological role in regulating glucagon secretion, especially in hyperglycemia." (PMID 36104518, 2022).
Hypoinsulinemia (1 paper, 2021). A decreased concentration of insulin in the blood. "Specifically, hypoinsulinemia reduced the thickness of the OE, the number of OSNs, and the number of OMP-positive cells." (PMID 33906971, 2021).
non-small cell lung carcinoma (1 paper, 2020). A group of at least three distinct histological types of lung cancer, including non-small cell squamous cell carcinoma, adenocarcinoma, and large cell carcinoma. "OMP-18R5 (Vantictumab) targets the FZD1, FZD2, FZD5, FZD7, and FZD8 frizzled protein receptors to block WNT signaling are being investigated in phase I clinical trials in breast, pancreatic, and non-small cell lung cancer." (PMID 32758244, 2020).
osteosarcoma (1 paper, 2024). A usually aggressive malignant bone-forming mesenchymal neoplasm, predominantly affecting adolescents and young adults. "With OPSIMprops, we acquired projections of two sub-volumes of a U-2 OS osteosarcoma cell labeled with OMP-GFP, an outer membrane marker for mitochondria." (PMID 38553438, 2024).
reactive arthritis (1 paper, 2014). Reactive arthritis (ReA) is an autoimmune disorder belonging to the group of seronegative spondyloarthropathies and is characterized by the classic triad of arthritis, urethritis and conjunctivitis. "Characterization of the OMP-immunoreactive fractions in Salmonella induced reactive arthritis by SDS-PAGE and MALDI-TOF MS." (PMID 25196519, 2014).
Respiratory tract infection (1 paper, 2025). An infection of the upper or lower respiratory tract. "OMP CD contributes to the bacterium’s resistance to adverse conditions, especially serum complement, and is highly associated with respiratory tract infections." (PMID 41465185, 2025).
infection (8 papers, 2017 to 2024). The state of being infected such as from the introduction of a foreign agent such as serum, vaccine, antigenic substance or organism. "Kinetic studies of the immune response to OMP revealed an increase in T cell number at 6 days following infection." (PMID 39440975, 2024). "Infection with an EGFP-tagged MCMV showed infection of OMP+ ONs, that extend their dendrites above the olfactory mucus." (PMID 36146741, 2022). "Twenty-seven peptides were related to protection (of which 7 were OMP-derived and 17 from PMP) since they were associated with effects related to Ct elimination (LO of infection, GP of clearance and LP of persistence)." (PMID 34145318, 2021). "Mice immunised with OMP+ CIA06 showed 60 to 90% survival after 8 days of infection with P. aeruginosa, while mice given OMP + alum showed 20 to 50% survival." (PMID 33291484, 2020). "Phage GSP032 could not propagate on S. Enteritidis mutants which lack LPS synthesis genes or the OMP gene tolC, indicating that both LPS and TolC are required for infection." (PMID 36165776, 2022). "SARS-CoV-2 was detected in olfactory nerve bundles close to the neuroepithelium, as demonstrated by the co-localization of SARS-CoV-2 nucleoprotein antigen and OMP+ sensory neuron axons reaching the olfactory bulb, consistent with a retrograde infection of axons." (PMID 33941622, 2021). "We report here the unexpected finding that after high-dose infection the attenuated Type 1 parasite, OMP, emerges as a virulent Toxoplasma strain in the absence of an intact T cell compartment." (PMID 39440975, 2024). "We did not observe any infection of TUJI or OMP positive neurons in the olfactory epithelium." (PMID 38172412, 2024). "Together, these results suggest that a lack of clearance of OMP parasites in Rag1−/− mice ultimately promoted a ~10-fold expansion of OMP parasites in the peritoneal cavity after 12 days of infection due to the ability of OMP to replicate at a very slow rate in low uracil concentration environments." (PMID 39440975, 2024).
tumor (5 papers, 2016 to 2025). "A significant increase in resistance to tumor development was observed in ROP18 deficient OMP parasites compared to mycalolide B treated ROP18 deficient OMP parasites." (PMID 27447180, 2016). "OMP-54F28 (ipafricept), a Fzd8 protein fused with immunoglobulin IgG1, has been shown to inhibit tumour proliferation by binding to Fzd receptors on solid tumours." (PMID 38927266, 2024). "Pancytokeratin (Pan-CK), cytokeratin 7 (CK7), cytokeratin 18 (CK18), olfactory marker protein (OMP) and Kiel 67 were examined in ENA tumours to clarify the immunohistochemical characteristics of ENA, analyse the tumour origin and screen for suitable antibodies for ENA tumour cell identification." (PMID 40144068, 2025). "OMP-18R5 (vantictumab) is a monoclonal antibody aimed at inhibiting Fzd receptors and blocking the activation of the canonical WNT signalling in multiple tumour types, such as in CRC, BC, and pancreatic cancer (PC)." (PMID 38927266, 2024). "Additionally, patients with prolactinoma lacked OMP expression in tumor tissues with hyperactivated ERK1/2 signaling." (PMID 29622766, 2018).
OMP also shares sentences with these, for which no sentence is quoted: cancer (1 paper); COVID-19 (1); dementia (1); endocarditis (1); experimental autoimmune encephalomyelitis (1); liver cancer (1); liver fibrosis (1); neuroendocrine carcinoma (1); Obesity (1); pituitary adenoma (1); Q fever (1); Rickettsialpox (1); schizophrenia (1); Sepsis (1); tetanus (1).